INPP5A (inositol polyphosphate-5-phosphatase A)
Description:
Phosphatase that specifically hydrolyzes the 5-phosphate of inositol 1,4,5-trisphosphate to inositol 1,4-bisphosphate, and inositol 1,3,4,5-tetrasphosphate to inositol 1,3,4-trisphosphate. Plays a crucial role in the survival of cerebellar Purkinje cells (By similarity).
Synonyms: 5PTase
Tractability: Antibody: UniProt places it where antibodies can reach, with high confidence; its Gene Ontology location is reachable by antibodies, with high confidence; the Human Protein Atlas places it where antibodies can reach. PROTAC: ubiquitination databases record sites on it; its protein half-life has been measured; a small molecule that binds it is known.
Target class: Enzyme; Phosphatase
Gene: Protein-coding gene on chromosome 10 (132,537,772 to 132,783,480, forward strand). Ensembl gene ENSG00000068383.
Subcellular location: Cell membrane; Cell projection, dendrite
Subcellular location (Human Protein Atlas): Cytosol; Plasma membrane
Pathways (Reactome):
Metabolism: Synthesis of IP2, IP, and Ins in the cytosol
Gene Ontology:
Molecular function: inositol-1,3,4,5-tetrakisphosphate 5-phosphatase activity; inositol-1,4,5-trisphosphate 5-phosphatase activity; inositol-polyphosphate 5-phosphatase activity; PH domain binding; protein binding; phosphatase activity
Biological process: inositol phosphate metabolic process; negative regulation of calcium-mediated signaling; negative regulation of phospholipase C-activating G protein-coupled receptor signaling pathway; phosphatidylinositol dephosphorylation; phosphorus metabolic process
Cellular component: membrane; plasma membrane; dendrite
Genetic constraint (gnomAD): Loss-of-function variants: 8 observed, 40.56 expected, observed/expected ratio (o/e) 0.2, 90% interval 0.12 to 0.36. The upper end of that interval is the gene's LOEUF score, 0.36, which puts it in group 1 of 6, group 1 being the genes least tolerant of losing a copy. Missense variants: 289 observed, 394.48 expected, observed/expected ratio (o/e) 0.73, 90% interval 0.67 to 0.81. Synonymous variants: 132 observed, 145.64 expected, observed/expected ratio (o/e) 0.91, 90% interval 0.79 to 1.05.
Homologues: Orthologues: mouse Inpp5a (97% identical), rat Inpp5a (97% identical), macaque INPP5A (95% identical), guinea pig INPP5A (92% identical), chimpanzee INPP5A (87% identical), pig INPP5A (85% identical), dog INPP5A (84% identical), tropical clawed frog inpp5a (84% identical), Drosophila melanogaster 5PtaseI (46% identical), Caenorhabditis elegans ipp-5 (39% identical), Caenorhabditis elegans C01B10.3 (22% identical).
Diseases named in the same sentence as INPP5A in open-access papers:
INPP5A is named in the same sentence as 31 diseases in open-access papers, as found by Europe PMC text mining. Sharing a sentence is not in itself a finding about the gene and the disease. The quoted sentences say what the papers report.
Ataxia (8 papers, 2020 to 2026). Ataxia refers to impaired coordination of voluntary muscle movement. "INPP5A is highly expressed in Purkinje cells of cerebellum, and in mice studies its deletion have been shown to cause ataxia and cerebellar degeneration." (PMID 39371129, 2024). "In mice, the deletion of Inpp5a causes perinatal lethality in 90% of the homozygous mutants, early onset ataxia and relatively small stature in surviving mutants." (PMID 34621295, 2021). "Deletion of INPP5A leads to PCs degeneration and ataxia in mice and contributes to cerebellar degeneration in Spinocerebellar ataxia type 17 (SCA17) mice, whereas overexpression of INPP5A in the cerebellum ameliorated PCs degeneration in SCA17 knock-in mice." (PMID 34421574, 2021). "In the pathogenesis of SCA17, overexpression of INPP5A ameliorated PCs degeneration and rescued cerebellar ataxia." (PMID 34421574, 2021).
cutaneous squamous cell carcinoma (5 papers, 2013 to 2024). "Deletion of a region encoding INPP5A on chromosome 10q26 is reported in cutaneous squamous cell carcinoma and brain tumors." (PMID 36437782, 2022). "Loss of INPP5A expression predicts poor overall survival in recurrent and metastatic disease of cutaneous squamous cell carcinoma." (PMID 34996491, 2022). "Mutations in INPP5A have been found in several cancers, and loss of the gene has been identified as an early event of human cutaneous squamous cell carcinoma." (PMID 25955013, 2015). "It was shown that loss of INPP5A was an early event in development of cutaneous squamous cell carcinoma." (PMID 24358143, 2013). "INPP5A was found to be lost in cutaneous squamous cell carcinoma, glioblastoma and leukemia, but its precise role in promoting tumorigenicity is yet to be demonstrated." (PMID 38233483, 2024). "A progressive reduction in INPP5A expression level plays a significant role in the progression of the localized to metastatic oropharyngeal SCC and cutaneous squamous cell carcinoma, which associates with invasive tumor behavior and poor clinical outcomes." (PMID 36437782, 2022).
cervical cancer (4 papers, 2020 to 2024). A primary or metastatic malignant neoplasm involving the cervix. "The miR-181a-5p can also increase cell proliferation and invasion and inhibit the apoptosis of cervical cancer cells by regulating INPP5A." (PMID 36313765, 2022). "INPP5A could be treated as the target of miR‐181a‐5p in regulation on the progression of cervical cancer." (PMID 32285560, 2020).
cerebellar degeneration (3 papers, 2020 to 2025). Degeneration of the cerebellum. "INPP5A is a cell type specific protein that is highly abundant in PCs and is involved in cerebellar degeneration." (PMID 34421574, 2021). "Previous studies have shown that INPP5A deletion leads to cerebellar degeneration." (PMID 34421574, 2021).
glioblastoma (2 papers, 2013 to 2024). The most malignant astrocytic tumor (WHO grade IV). "On the other hand, alterations of SGCG, HTR4, ITGB1, CPS1, PROS1 and INPP5A were detected predominantly in anaplastic astrocytoma, while alterations of PDE4D were present in both glioblastoma subtypes." (PMID 24358143, 2013).
melanoma (2 papers, 2024 to 2025). A malignant, usually aggressive tumor composed of atypical, neoplastic melanocytes. "Key findings include the potential therapeutic value of FTIs for NRAS-mutated melanoma and GNAQ/GNA11-mutated uveal melanoma by inhibiting INPP5A farnesylation." (PMID 39995872, 2025).
squamous cell carcinoma (2 papers, 2022 to 2025). A carcinoma arising from squamous epithelial cells. "Finally, our data may help to explain the benefits of depletion of INPP5A in cancers such as squamous cell carcinoma." (PMID 35182526, 2022).
uveal melanoma (2 papers, 2024 to 2025). A melanoma derived from melanocytes of the uveal tract. "Manchado and colleagues combine CRISPR screening and transcriptomics to identify INPP5A as a dependency and therapeutic target in uveal melanoma driven by mutations in GNAQ/GNA11 and show that IP4 levels correlate with sensitivity to INPP5A loss." (PMID 38233483, 2024). "INPP5A was recently identified as a drug target in uveal melanoma (UVM) with activating mutations in the guanosine nucleotide-binding protein Q gene (GNAQ) or its paralog guanosine nucleotide-binding protein alpha-11 gene (GNA11), which occur in approximately 90% of these cancers." (PMID 39995872, 2025).
actinic keratosis (1 paper, 2022). A precancerous lesion of the skin composed of atypical keratinocytes. "A reduction in INPP5A expression level emerges to be a prior event in the SCC development, and loss of its expression is found in the earliest stage of SCC, and actinic keratosis." (PMID 36437782, 2022).
anaplastic astrocytoma (1 paper, 2013). "The most frequently present alteration was in INPP5A gene, detected in 43.3% of patients, predominantly in patients with anaplastic astrocytoma (62.5% vs. 36.4% of GBM patients), and patients with high level of genomic instability." (PMID 24358143, 2013).
depression (1 paper, 2020). "The strongest GWAS hit is rs4497325, and for the associated mode 4562, the peak SNP is (the immediately-neighbouring) rs7096828; this is an eQTL of INPP5A, which is involved in DNA methylation in neurons, associated with aging and depression." (PMID 32134384, 2020).
esophageal cancer (1 paper, 2018). A primary or metastatic malignant neoplasm involving the esophagus. "Furthermore, DUXAP8 is positively related to MAGEA4, GABRA3 expression, and negatively related to INPP5A, TIMP4 expression in esophageal cancer; LINC00460 is positively related to ITGA3, LAMC2 expression, and negatively related to FOXO4, KLF15 expression in esophageal cancer." (PMID 29926523, 2018).
Obesity (1 paper, 2025). Accumulation of substantial excess body fat. "GWAS have identified four of these (INPP5A, ZDHHC2, IQCF6, and PRKCH) to be associated with BMI or obesity." (PMID 40892850, 2025).
Parkinson disease (1 paper, 2025). A progressive degenerative disorder of the central nervous system characterized by loss of dopamine producing neurons in the substantia nigra and the presence of Lewy bodies in the substantia nigra and locus coeruleus. "Those variants are in the vicinity of INPP5A, a gene implicated in calcium signaling and in the risk for Parkinson disease." (PMID 40103583, 2025).
sarcoma (1 paper, 2022). A usually aggressive malignant neoplasm of the soft tissue or bone. "Through such method, genes highly associated with sarcoma subtypes, such as PRKAR1B, INPP5A, GLI3, and other genes, were obtained." (PMID 36619306, 2022). "The specific expression of genes obtained from the annotation of highly correlated methylation site features, such as PRKAR1B, INPP5A, and GLI3, was proven to be associated with sarcoma by publications." (PMID 36619306, 2022). "Other studies have found that gene expression of INPP5A has an important role in sarcoma classification." (PMID 36619306, 2022).
skin cutaneous melanoma (1 paper, 2025). "We subsequently determined that tumors from UM patients upregulate and require INPP5A by comparing nonredundant, curated sets of tumor transcriptomic and genomic data (cBioPortal) from UM (80 samples) and skin cutaneous melanoma (SKCM; 488 samples) patients." (PMID 40812428, 2025).
tumor (10 papers, 2013 to 2026). "Only one INPP5A mutation occurred in a UM tumor, which encoded a Q412L substitution at the C terminus, distal to the catalytic domain." (PMID 40812428, 2025). "Significantly, the low level of INPP5A protein expression was associated with age and tumor size." (PMID 36437782, 2022). "In addition, the INPP5A mRNA expression was inversely associated with not only the high grade of tumor differentiation (p = 0.017) but also tumor invasion (p < 0.001)." (PMID 36437782, 2022). "In vivo experiments further showed that inhibition of INPP5A dramatically reduced tumor burden and metastasis in a mouse model of GNAQ or GNA11-mutant UVM." (PMID 39995872, 2025). "Tumor xenografts expressing INPP5A shRNAs displayed reduced mRNA levels and significant tumor growth inhibition compared to those harboring a control shRNA." (PMID 38233483, 2024). "In a nude mice model, its silencing was shown to increase intracellular inositol polyphosphate 5-phosphatase (INPP5A) and inositol 1,3,4,5-tetrakisphosphate, leading to cell transformation and tumor formation." (PMID 37835379, 2023). "The associations between INPP5A protein expression and other clinical variables in ESCC patients indicated that the underexpression of the INPP5A protein was significantly correlated with age (p = 0.055) and tumor size (p = 0.037)." (PMID 36437782, 2022). "As a consequence, our data collectively uncover the crucial regulatory role of INPP5A as a novel tumor suppressor gene in ESCC." (PMID 36437782, 2022). "In vitro and in vivo investigations have demonstrated that INPP5A downregulation leads to cellular transformation and cancer development, suggesting a vital role for INPP5A as a tumor suppressor gene through preventing cancer cell proliferation." (PMID 36437782, 2022). "The mRNA expression level of INPP5A was significantly lower in ESCC tissues compared to the matched adjacent non-tumor esophageal tissues (mRNA expression, p = 0.018)." (PMID 36437782, 2022). "We next investigated the impact of INPP5A inhibition on UM tumor growth in vivo." (PMID 38233483, 2024). "Silencing INPP5A substantially inhibited both UM metastasis formation and growth of established metastases, even when treatment onset was delayed until the mice exhibited high metastatic tumor burden." (PMID 38233483, 2024). "Importantly, regrowing tumors have restored their INPP5A mRNA levels, further substantiating that UM cells require INPP5A for tumor maintenance in vivo." (PMID 38233483, 2024). "However, inositol polyphosphate 5-phosphatase (INPP5A) has been shown to have tumor-suppressive effects." (PMID 37835379, 2023). "Furthermore, the decreased mRNA expression level of INPP5A was not only inversely correlated with the histologic grade and depth of invasion but also with patients’ sex, location, and tumor size." (PMID 36437782, 2022). "NDRG1 contributes to tumor aggressiveness by cell proliferation and lipid metabolism regulation, whereas GAPVD1, INPP5A, TCN1, SAV1, RBBP8, SPIB, and UBE2A also exhibit oncogenic or tumor-suppressive properties associated with prognosis." (PMID 41511940, 2026). "To investigate the clinical significance of INPP5A as a therapeutic target, we examined the steady-state levels of IP4 in UM patient-derived xenografts (PDXs) and patients’ tumor samples." (PMID 38233483, 2024). "We found that INPP5A mRNA expression is significantly (p < 0.001) higher in UM tumors compared with SKCM tumors and that INPP5A is genetically preserved in UM tumors compared with SKCM tumors (χ2 < 0.001) as indicated by analysis of tumor genomic data." (PMID 40812428, 2025). "The protein expression level of INPP5A in ESCC tissues was significantly lower than that of the non-tumor esophageal tissues (p = 0.001)." (PMID 36437782, 2022). "Notably, ITGB8, DICER1, INPP5A, PIK3R1, and TIMP2 are key tumor suppressors that were among up-regulated CRGs following CBX2 knockdown." (PMID 26877821, 2016).
tumor (continued). "INPP5A is located in the short arm of chromosome 10 (10q26.3), and LOH of this region represent the most frequent genetic abnormality in both primary and secondary GBM, due to the presence of multiple tumor suppressor genes in this chromosomal region." (PMID 24358143, 2013). "INPP5A, HLA-G1, MMP-21, and IL-10 showed to be the most appropriate candidates to discriminate tumor/non-tumor groups due to the total AUCs of all combinations (>60%)." (PMID 36437782, 2022).
cancer (9 papers, 2011 to 2025). A tumor composed of atypical neoplastic, often pleomorphic cells that invade other tissues. "Still, previous reports on cancer-association in humans and the function of the encoded protein, at least for INPP5A and CYP2E1, propose that they may play a part in the CMT pathogenesis." (PMID 25955013, 2015). "Further studies in larger series of patients are warranted to elucidate this question and determine the specific role of those cancer associated genes (INPP5A, CDX1, MB, CAMK2A, APOL6 vs. VPS53, FAM57A, GEMIN4, SFRS13, ELP2P, GLOD4, CSF2RA and IL3RA), differentially altered in both groups of tumors." (PMID 21811587, 2011). "Loss of INPP5A in cancer cells may help to fuel cell growth and division under restricted supply of nutrients by promoting the lysosome-mediated degradation of proteins internalized via macropinocytosis into amino acids, which in turn serve to sustain mTORC1 activity." (PMID 35182526, 2022). "Based on the integral role of each gene in different cancers, we took the opportunity to focus on novel potential regulatory crosstalk among the INPP5A, HLA-G1, IL-10, and MMP-21 in ESCC." (PMID 36437782, 2022). "Importantly, INPP5A was recently shown to be a highly specific vulnerability in UVM with activating mutations in GNAQ/GNA11, which occur in 90% of these cancers." (PMID 39995872, 2025). "This study highlighted INPP5A as a target of cancer therapy in UVM." (PMID 39995872, 2025). "Here, we performed genome-scale CRISPR screens along with computational analyses of cancer dependency and gene expression datasets to identify the inositol-metabolizing phosphatase INPP5A as a selective dependency in GNAQ/11-mutant UM cells in vitro and in vivo." (PMID 38233483, 2024). "Our findings uncover INPP5A as a synthetic lethal vulnerability and a potential therapeutic target for GNAQ/11-mutant-driven cancers." (PMID 38233483, 2024). "The genes COL9A3, INPP5A and CYP2E1 were found in the regions with most frequently occurring homozygous deletions in each of the groups of hyperplasias, benign and malignant tumours." (PMID 25955013, 2015). "Besides, there were significant correlations between the concomitant expression profiles of INPP5A/HLA-G1, INPP5A/IL-10, and INPP5A/MMP-21 in the patients with invaded cancer cells into the adventitia." (PMID 36437782, 2022).
cardiovascular disease (1 paper, 2025). "INPP5A has also been associated with of cardiovascular disease." (PMID 40892850, 2025).
neurodegenerative disease (1 paper, 2021). A disorder of the central nervous system characterized by gradual and progressive loss of neural tissue and neurologic function. "Reduced expression of INPP5A has also been found to be involved in spinocerebellar ataxia, a group of neurodegenerative diseases that includes forms intimately linked to defective Golgi-to-plasma membrane trafficking." (PMID 33976123, 2021).
INPP5A also shares sentences with these, for which no sentence is quoted: glial tumors (2 papers); glioma (2); leukemia (2); spinocerebellar ataxia type 17 (2); brain tumors (1); cerebellar ataxia (1); esophageal squamous cell carcinoma (1); hearing loss (1); mammary tumour (1); metastatic disease (1); systemic sclerosis (1).